GATA3 (GATA binding protein 3)
Diseases named in the same sentence as GATA3 in open-access papers (continued):
Sharing a sentence is not in itself a finding about the gene and the disease.
dermatitis (5 papers, 2011 to 2024). An inflammatory process affecting the skin. "All mice with oxazolone-induced dermatitis had increased proportions of GATA3+ Th2 cells compared to the vehicle treated mice, CS-GM mice had a significantly higher proportion of Th2 cells compared to VD-GM mice." (PMID 37889696, 2023). "In our study, we found that HB markedly suppressed mRNA expression of IL-4, IL-13, and the transcription factor GATA3 known to drive immune cells to produce a type 2 immune response in dermatitis skin tissue." (PMID 34531749, 2021). "Since NGO application constrains quantitative and qualitative alterations in Treg cells, such as a decreased Foxp3 and increased GATA3 expression during skin inflammation, it would be worthwhile to investigate whether NGO can regulate the progression of FA." (PMID 39199350, 2024). "Here, we showed that in vivo NGO treatment induces a decrease in the antigen-specific Th2 population and GATA3-expressing Treg cells in Balb/c mice during OVA/Alum immunization, consequently suppressing the outcome of OVA-induced skin inflammation." (PMID 39199350, 2024). "However, the expression levels of GATA3 and ST2 in CD4+ T cells and the numbers of all subsets of inflammatory cells were reduced in Raptor cKO mice, supporting that mTORC1 was essential for the activation of immune cells in skin inflammation induced by MC903." (PMID 36983043, 2023).
ductal carcinoma (5 papers, 2018 to 2025). "In case #2, metastatic breast ductal adenocarcinoma showed relatively monomorphic cells immunoreactive for GATA3 and ER." (PMID 40028792, 2025). "They reported GATA3 labeling in two-thirds of primary ductal carcinomas, including triple-negative samples." (PMID 34094972, 2021).
food allergy (5 papers, 2017 to 2025). Gastrointestinal disturbances, skin eruptions, or shock due to allergic reactions to allergens in food. "Interestingly, the Foxp3/Rorγt (except for the treated group)and Foxp3/Gata3 ratios were significantly increased in the groups received C. butyricum orally as compared to the food allergy group indicating an increase in Treg-associated responses." (PMID 28250847, 2017). "Food allergy (FA)-sensitive mice display an increased frequency of GATA Binding protein 3 (GATA3)+ Treg cells in their mesenteric lymph nodes (MLN) after OVA sensitization." (PMID 39199350, 2024). "The food allergy groups showed a Th2-skewed immune response represented by a significant increase in Gata3/Tbet ratio as compared to control group." (PMID 28250847, 2017). "Th2 dominance was observed in the food allergy group represented by a significant decrease in Th1 and Treg transcription factors and high Gata3/Tbet ratio." (PMID 28250847, 2017). "The expression of Th1-(Tbet) and Treg-(Foxp3) transcription factors was significantly decreased in the food allergy group as compared to the control group, whereas the expression of Th2-(Gata3) and Th17-(Rorγt) transcription factors increased dramatically." (PMID 28250847, 2017). "Moreover, WASp-deficient FOXP3+ Tregs has been shown to drive Th2-mediated intestinal inflammation and food allergy, marked by increased GATA-3, IL-4, and IgE levels." (PMID 41035657, 2025).
germ cell tumor (5 papers, 2020 to 2025). A benign or malignant, gonadal or extragonadal neoplasm that originates from germ cells. "Additional negativity for CK20, GATA3, and glypican-3 further excluded metastatic gastrointestinal or germ cell tumors." (PMID 41149460, 2025).
Hodgkins lymphoma (5 papers, 2016 to 2024). A heterogeneous group of malignant lymphoid neoplasms of B-cell origin characterized histologically by the presence of Hodgkin and Reed-Sternberg (HRS) cells in the vast majority of cases. "The constitutive induction of NFkB and Notch-1 led to an aberrant increase in GATA3 levels within Reed–Sternberg cells accompanied by a massive amount of IL-13, ending up with typical signaling of Hodgkin lymphoma." (PMID 39768217, 2024). "Elevated GATA3 expressions have been detected in B-cell malignancies, including Hodgkin lymphoma, as well." (PMID 39768217, 2024).
liver fibrosis (5 papers, 2017 to 2025). "Therefore, we inferred that sericin might exert its anti-liver fibrosis effect by targeting GATA3 and reducing inflammatory molecules in the liver." (PMID 38443583, 2024). "In addition, GATA-3 was shown to regulate microRNA-370/high mobility group box 1 (miR-370/HMGB1) signaling pathway, promoting autophagy and hepatic stellate cell activation, which contributes to liver fibrosis." (PMID 41514930, 2025).
lung squamous cell carcinoma (5 papers, 2015 to 2024). "The analogy could also be extended to the lung squamous cell carcinoma subtype and suggests that downregulation of FOXA1 and GATA3 as well as upregulation/activation of EGFR and STAT3 as fundamental components of a generalized basal/squamous-like tumor phenotype." (PMID 26008846, 2015).
nasal polyps (5 papers, 2009 to 2024). "For intragroup comparison, we observed a significant elevation of T-bet and GATA-3 mRNA, but a significant reduction of Foxp3 mRNA in nasal polyps compared to the control mucosa (P < 0.05 by the unpaired t-test)." (PMID 19250527, 2009). "Since the functional development of T cells is regulated by specific transcription factors, we quantified the levels of T-bet, GATA-3, Foxp3, and RORγt mRNA in rapamycin-stimulated nasal polyps by real time RT-PCR." (PMID 19250527, 2009). "Subsequently, we examined the levels of T-bet, GATA-3, Foxp3, and RORγt mRNA expression in cultured nasal polyps." (PMID 19250527, 2009). "After treatment with rapamycin, we found that the level of Foxp3 mRNA was increased by as much as 5.5-fold in nasal polyps, while the levels of T-bet and GATA-3 mRNA decreased, revealing an inverse inter-modulation tendency." (PMID 19250527, 2009). "The expression of GATA3 mRNA in nasal polyps reported previously varies from paper to paper." (PMID 26594227, 2015). "Interestingly, our results, presented characteristically high levels of T-bet/GATA-3 mRNA and low levels of Foxp3 mRNA in nasal polyps, which is consistent with previous reports." (PMID 19250527, 2009). "In order to evaluate the possible association between inhibition of mTOR signaling and Foxp3+ Treg expansion, we investigated a series of proteins, including PTEN, PI3K, pAkt, pmTOR, p4E-BP1, T-bet, GATA-3, and Foxp3 in rapamycin-stimulated nasal polyps by western blot analysis." (PMID 19250527, 2009). "Furthermore, Foxp3 expression was significantly upregulated (3.3-fold in nasal polyps and 2.3-fold in control tissues; P < 0.05 by the paired t-test) after rapamycin stimulation, while T-bet and GATA-3 expression decreased correspondingly (P < 0.05 by the paired t-test)." (PMID 19250527, 2009). "Thus, to further investigate the phenotype of non-asthmatic Korean nasal polyps, we analyzed the mRNA expression of transcription factors, including T-bet, GATA-3, and RORC in UP tissues from CRS patients." (PMID 25361058, 2014). "There were also significant increases in GATA3, IL4, IL5, and IL17 gene expression levels in nasal polyp tissue from the AERD group compared with the non-AERD group." (PMID 38360807, 2024).
renal carcinoma (5 papers, 2020 to 2024). A carcinoma arising from the epithelium of the renal parenchyma or the renal pelvis. "For instance, ELK4, CBFB, IFI16, PRRX1, AEBP1, and GATA3 expression was associated with an unfavourable outcome in renal cancer revealing the significance of these TFs (pink and blue colours represent unfavourable and favourable prognosis, respectively)." (PMID 35201514, 2021). "On a similar note, a significant association between the expression of ELK4, CBFB, IFI16, PRRX1, AEBP1, and GATA3 with an unfavourable outcome in renal cancer has been identified in previous reports." (PMID 35201514, 2021). "In addition, in the normal fibroblast-conditioned media treated with renal cancer cells, GATA3 was increased in surrounding normal tissues but downregulated at both the mRNA and protein levels." (PMID 39090094, 2024). "Taken together, inhibiting the IL6/STAT3 signaling pathway and promoting GATA3 signals may be a therapeutic intervention for the treatment of renal cancer cell metastasis." (PMID 31636361, 2020). "GATA3 overexpression significantly reduced STAT3 phosphorylation and attenuated the migration in both renal cancer cell and IL6-stimulated renal cancer cell." (PMID 31636361, 2020). "In contrast, GATA3 was downregulated at both mRNA and protein levels in the normal fibroblast-conditioned medium treated with renal cancer cells, but upregulated in adjacent normal tissues." (PMID 31636361, 2020).
rhinitis (5 papers, 2011 to 2024). An inflammation of the mucous membrane lining the nose, usually associated with nasal discharge. "It has been elucidated that SNP-SNP interactions between GATA3 and IL13 polymorphisms can influence the risk of childhood rhinitis." (PMID 21738793, 2011).
signet ring cell carcinoma (5 papers, 2014 to 2024). A usually aggressive, poorly differentiated invasive adenocarcinoma characterized by the presence of malignant glandular cells in which the nucleus is pressed to one side by the presence of intracytoplasmic mucus. "UC with glandular differentiation, lymphoepithelioma-like UC, sarcomatoid UC, and signet ring cell carcinoma had GATA3 expression rates of 47.4%, 30.0%, 40.7%, and 40.9%, respectively." (PMID 37629741, 2023). "The colonic lesion had a histopathological appearance similar to that of signet ring cell carcinoma and was ER-positive, PgR-negative, and GATA-binding protein 3 (GATA3) -positive." (PMID 37845365, 2023).
skin tumor (5 papers, 2019 to 2025). "Interestingly, prostate and skin tumor phenotypes could also be dampened by overexpression of GATA3 in these tissues indicating that both Gata3 and BMP5 are key players in Pten-deficient cancer progression." (PMID 32894216, 2020). "It is worth noting that only GATA3 was significantly associated with the survival of SKCM, another skin cancer." (PMID 34301206, 2021).
soft tissue sarcoma (5 papers, 2016 to 2025). A malignant neoplasm arising from muscle tissue, adipose tissue, blood vessels, fibrous tissue, or other supportive tissues excluding the bones. "For instance, GATA3 expression was detected in various soft tissue sarcomas (STS) and was correlated with unfavorable clinicopathological parameters and reduced disease-free survival." (PMID 41303462, 2025). "Similarly, results obtained using downregulated DEGs include transcription factors previously associated with poor prognosis for human soft tissue sarcomas (GATA4, GATA3)." (PMID 36099287, 2022). "However, no previous studies have evaluated the clinicopathological importance of GATA3 expression in soft tissue sarcomas (STS) patients." (PMID 27249072, 2016). "In agreement with previous reports, our data expand on earlier evidence of SOX9, GATA3, and GATA4 dysregulation in soft tissue sarcomas." (PMID 41303462, 2025).
T-cell leukemia (5 papers, 2014 to 2023). A malignant disease of the T-lymphocytes in the bone marrow, thymus, and/or blood. "Fra-2 enhances CCR4 expression in adult T-cell leukemia, and HTLV-1 viral factor-generated GATA3 stimulates CCR4 expression in CD4+ T cells." (PMID 35222362, 2022). "GATA2 and GATA1 are implicated at many (up to 90%) of the TAL1-bound sites in normal hematopoietic cells, and GATA3 along with ETS1 and RUNX1 can direct TAL1 binding when it is aberrantly expressed in T-cell leukemias." (PMID 25319994, 2014).
thyroid carcinoma (5 papers, 2018 to 2025). "IHC staining of the tumor in the neck showed diffuse expression of PAX8 and TTF1, indicating thyroid origin, and negative staining for thyroglobulin, calcitonin, PTH, and GATA3, which support a diagnosis of an oncocytic poorly differentiated thyroid carcinoma." (PMID 40277780, 2025). "Expression of GATA-3 supports a breast origin, while the absence of PAX-8 helps exclude primary thyroid carcinoma." (PMID 41556026, 2025).
type 1 diabetes (5 papers, 2014 to 2025). "Similarly, an effector memory Treg subset expressing HLA-DR, CCR4, CCR6, CXCR3, and GATA3 was increased in the high-risk group of patients with type 1 diabetes." (PMID 37189479, 2023). "Furthermore, AGL also increased GATA3 mRNA expression, while a decrease in T-bet and RAR-related orphan receptor gamma t (RORγt) mRNA expressions, suggesting prevention of type 1 diabetes by maintaining Th1/Th2/Th17 homeostasis." (PMID 28878680, 2017).
acute myeloid leukemia (4 papers, 2020 to 2026). Acute myeloid leukemia (AML) is a group of neoplasms arising from precursor cells committed to the myeloid cell-line differentiation. "Inactivation by the mutation or deletion of ETV6, RUNX1, and GATA3 has also been described in patients with Acute Myeloid Leukemia (AML) and correlates with poor outcomes in ETP-ALL." (PMID 35626079, 2022). "ETV6, RUNX1, and GATA3, described also in acute myeloid leukemia, are deleted or inactivated in ETP-ALL, and correlate with poor outcome: ETV6 (12p13) mutations account for ~25% of ETP-ALL, whilst RUNX1 (21q22), and GATA3 (10p14) mutations are less common." (PMID 32185137, 2020).
carcinoma in situ (4 papers, 2016 to 2023). "The GATA3 expression rate in carcinoma in situ was 0.956 (95% CI 0.878−0.985)." (PMID 37629741, 2023). "Among CD4+ T cells, the percentage of GATA3+FOXP3– cells and the percentage of GATA3+FOXP3+ cells were higher in invasive melanoma compared with in situ melanoma, while the percentage of GATA3–FOXP3+ cells remained similar." (PMID 36107619, 2022). "Melanoma in situ was negative for GATA3 but positive for S100, melan-A and HMB45 whereas EMPD had an opposite immunoprofile." (PMID 28693610, 2017).
endocervical adenocarcinoma (4 papers, 2021 to 2024). An adenocarcinoma that arises from the endocervix. "In an immunohistochemical study, four (5.1%) endometrial endometrioid carcinomas were positive for GATA3, and the expression of this marker was observed in 13 (12.9%) ovarian and 1 (11.1%) endocervical adenocarcinoma." (PMID 39118796, 2024). "HPV testing, p16, and GATA3 immunohistochemistry can be diagnostically useful in these cases, as mesonephric endocervical adenocarcinoma will be HPV-negative and p16-negative (or non–block-type) and typically positive for GATA3." (PMID 33570865, 2021). "In our study, ADRN-specific GATA3 was overexpressed in breast invasive carcinoma (BRCA), cervical squamous cell carcinoma and endocervical adenocarcinoma (CESC), testicular germ cell tumours (TGCT), STAD, PAAD, and THYM, data that we matched with the mutational profiles of these genes." (PMID 35201514, 2021).
gynecologic cancers (4 papers, 2021 to 2024). "Uterus didelphys has also been reported as a GATA3-associated disease." (PMID 39062799, 2024).
head and neck squamous cell carcinoma (4 papers, 2016 to 2025). A squamous cell carcinoma that arises from any of the following anatomic sites: lip and oral cavity, nasal cavity, paranasal sinuses, pharynx, larynx, and salivary glands. "In head and neck squamous cell carcinoma (HNSCC), GATA3 associates with HIF1α under hypoxia to inhibit the ubiquitination and proteasomal degradation of HIF1α, a mechanism independent of HIF1α prolyl-4-hydroxylation." (PMID 39942749, 2025). "In contrast, GATA3 enhances invasiveness of cells of head and neck squamous cell carcinoma and cancer cell stemness in ovarian high-grade serous carcinoma." (PMID 34595169, 2021). "In this study, we discover that GATA3 is upregulated in head and neck squamous cell carcinoma (HNSCC) and is an independent predictor for poor disease-free survival." (PMID 28263977, 2017). "In clinical samples, GATA3 expression positively correlates with HIF-1α and is an independent predictor for poor disease-free survival in head and neck squamous cell carcinoma (HNSCC)." (PMID 28263977, 2017).
infertile (4 papers, 2009 to 2024). "Elevated expression of GATA3 transcription factor was detected in Inc stimulated CD4+ T cells from CT-positive infertile women compared to CT-positive fertile women and controls." (PMID 19698128, 2009). "Positive correlation (P < 0.05) was found between Interferon-gamma and T-Bet levels in CT-positive fertile women and IL-4 mRNA and GATA3 levels in CT-positive infertile patients upon IncB and IncC stimulation." (PMID 19698128, 2009). "On stimulation of CD4+ T cells with IncB or IncC, IFN-γ and T-Bet levels were found to be positively correlated in CT-positive fertile women whereas IL-4 mRNA levels were positively correlated to GATA3 expression in CT-positive infertile women." (PMID 19698128, 2009). "Modulation of cytokines and transcription factors (T-bet and GATA-3) in CD4 enriched cervical cells of Chlamydia trachomatis infected fertile and infertile women upon stimulation with chlamydial inclusion membrane proteins B and C was reported." (PMID 32413046, 2020).
inflammatory bowel disease (4 papers, 2017 to 2025). A spectrum of small and large bowel inflammatory diseases of unknown etiology. "Two disease-related pathways — inflammatory bowel disease (cfa05321; GATA3, TLR4) and cancer pathways (cfa05222; COL4A1, E2F3, RARB) — were also enriched." (PMID 40764990, 2025). "The inflammatory bowel disease is highlighted (q-value = 0.015) through KEGG enrichment analysis using FABIO significant genes, and the involved genes are IL18RAP, IL4, GATA3, and SMAD3 (FABIO PIP = 1, 0.76, 1, and 0.75, respectively)." (PMID 39621803, 2024).
mycosis fungoides (4 papers, 2021 to 2025). Classical mycosis fungoides is the most common type of mycosis fungoides (MF), a form of cutaneous T-cell lymphoma, and is characterized by slow progression from patches to more infiltrated plaques and eventually to tumors. "The transcription factor GATA3 is negative or weakly positive in pc-ALCL, which is a useful finding in distinguishing it from CD30+ mycosis fungoides with large cell transformation that are typically strongly and diffusely positive for GATA3." (PMID 34572893, 2021). "GATA3 is strong and diffuse in mycosis fungoides with CD30+ large cell transformation but negative or only weakly positive in primary cutaneous ALCL." (PMID 37627126, 2023).
osteoarthritis (4 papers, 2014 to 2025). A noninflammatory degenerative joint disease occurring chiefly in older persons, characterized by degeneration of the articular cartilage, hypertrophy of bone at the margins and changes in the synovial membrane. "In another study, the effects of crocin on GATA-3 and T-bet expression in mononuclear cells of patients with osteoarthritis (OA) were investigated." (PMID 36311189, 2022). "We found that GATA3+ cells were present in the inflamed synovial tissue and were significantly higher in RA than in osteoarthritis patients." (PMID 27273006, 2016). "A similar distribution of CD20:CD3, CD4:CD8, and GATA3:T-bet was seen in perivascular regions in the synovium from patients with osteoarthritis with excessive synovial chronic inflammatory infiltrate." (PMID 25242891, 2014).
papillary renal cell carcinoma (4 papers, 2014 to 2025). A rare subtype of renal cell carcinoma, arising from the renal tubular epithelium and showing a papillary growth pattern, which typically manifests with hematuria, flank pain, palpable abdominal mass or nonspecific symptoms, such as fatigue, weight loss or fever. "Comparison of CGI methylation of GATA3 and GATA5 in ccRCC and papillary renal cell carcinoma showed significant statistical differences for the mean GATA3 (P=0.006) and GATA5 (P=0.015) relative methylation indices observed in both histological entities." (PMID 24549248, 2014). "In IHC analysis, this subtype, which the authors named “oncocytic low grade papillary renal cell carcinoma”, was positive for GATA3, negative for CA IX, and strongly and diffusely positive for ABCC2 (similarly to PRCC type II)." (PMID 40989704, 2025).